INS (insulin)
Diseases named in the same sentence as INS in open-access papers (continued):
Sharing a sentence is not in itself a finding about the gene and the disease.
Insulin resistance (continued). "We hypothesize that long-term insulin injection may induce or exacerbate insulin resistance, potentially contributing to chronic injury and fibrosis." (PMID 40836299, 2025). "This dimorphism arises from opposing actions of gonadal steroids: testosterone enhances orexin neuron excitability and promotes insulin resistance upon orexin loss, whereas 17β-estradiol upregulates OX1R expression and potentiates insulin-sensitizing and β-cell-protective effects of orexin-A." (PMID 41438219, 2025). "Similarly, inflammatory pathways such as TNF, JNK, and suppressor of cytokine signaling (SOCS), which are activated by LPS, aberrantly phosphorylate IRS, leading to reduced insulin signaling and the development of insulin resistance." (PMID 40458405, 2025). "Insulin resistance was assessed using an intraperitoneal exogenous insulin tolerance test." (PMID 40776976, 2025). "Studies reported lower fasting glucose, insulin levels, and HOMA-IR, suggesting that EVOO-enriched MD contributes to enhanced glucose metabolism an essential component in MASLD which is closely linked to insulin resistance." (PMID 41010458, 2025). "The antidiabetic effect was proved by the improvement that occurred in insulin resistance and the increase in insulin sensitivity in diabetic cells, as well as amelioration of the pancreatic islets’ histological integrity and the insulin formation by the recovered β-cells." (PMID 40430475, 2025). "Therefore, in this study, we aimed to investigate the relationships between insulin secretion and/or insulin resistance and between cortisol or aldosterone levels in patients with untreated type 2 diabetes." (PMID 40296149, 2025). "In addition, a positive regulation of insulin secretion can directly respond to insulin resistance and restore glycemia." (PMID 40943107, 2025). "The accumulation of oxidants, particularly in skeletal muscle and adipose tissue, is linked to the complex development of insulin resistance, with a brief surge of H2O2 generated upon insulin release, exposing cells to reactive oxygen species at low concentrations for a short duration." (PMID 40283443, 2025). "In addition, all data discussing any effects on insulin, insulin resistance, or insulin sensitivity were included." (PMID 41322229, 2025). "Moreover, insulin resistance interferes with brain insulin signaling, impairing memory consolidation and favouring the aggregation of neurotoxic proteins such as beta-amyloid." (PMID 40892247, 2025). "Additionally, oxidative stress can provoke inflammatory responses, further worsening insulin resistance through the activation of pro-inflammatory cytokines that disrupt insulin signalling." (PMID 40862129, 2025). "These plant-derived phenolic compounds may regulate insulin action and metabolism in insulin-sensitive tissues, exerting effects that prevent or treat insulin resistance and its related diseases." (PMID 40896190, 2025). "The production of endocannabinoids in adipocytes is under the negative control of insulin, and their increased level is associated with the development of insulin resistance." (PMID 40283681, 2025). "Reduced insulin production is also described in these patients due to the accumulation of lipid droplets in beta cells and the overload suffered by beta cells when trying to compensate for insulin resistance with hyperinsulinemia." (PMID 40426986, 2025). "Finally, 51 study participants (29 BSE, 22 placebo) had the typical characteristics of mild age-related diabetes (MARD), with comparatively low BMI, insulin resistance, fatty liver index and insulin secretion." (PMID 39929977, 2025). "In addition, impaired insulin secretion in response to glucose stimulation and accelerated development of insulin resistance were observed." (PMID 40807271, 2025).
Insulin resistance (continued). "Animal model studies have demonstrated that metabolic acidosis accounts for impairing the binding of insulin to its receptors, which highlighted the hypothesis regarding metabolic acidosis may have a potential to promote insulin resistance." (PMID 40491860, 2025). "The role of insulin resistance in driving insulin secretion is widely acknowledged." (PMID 40568093, 2025). "One key pathway is insulin resistance and hyperinsulinemia: adiposity, especially visceral fat, drives chronic insulin resistance, leading to elevated circulating insulin and IGF-1 levels, which have mitogenic and anti-apoptotic effects on colonic epithelial cells." (PMID 41041441, 2025). "Interestingly in some literature, the competition to bind to glycoprotein receptor INS-R between insulin and TNF-α is also noted and cited as a cause of insulin resistance." (PMID 40136728, 2025). "MSCs alleviate insulin resistance in T2DM patients by enhancing insulin signaling pathways." (PMID 40290901, 2025). "At 2 years of follow-up, the effect of the CC genotype on changes in insulin and HOMA-IR remained significant in the highest-carbohydrate-diet group, demonstrating that the IRS1 variant rs2943641 may improve insulin resistance in response to weight-loss diets." (PMID 40732974, 2025). "These factors are associated with a cluster of metabolic abnormalities, including glucose intolerance, elevated insulin levels, insulin resistance, hypertriglyceridemia, reduced levels of high-density lipoprotein (HDL), and increased concentrations of low-density lipoprotein (LDL)." (PMID 40649724, 2025). "Furthermore, the higher levels of insulin and C-peptide observed in the patient group may be explained by the presence of hyperglycemia and type 2 diabetes in this group, as well as a higher prevalence of obesity and central obesity, which are commonly associated with increased insulin resistance." (PMID 40870524, 2025). "However, knowledge on this topic is still limited, and there is a need for multi-center studies to evaluate the effects of GLP-1 receptor agonists on improving insulin signaling across different body tissues in individuals with insulin resistance." (PMID 40725728, 2025). "This dual effect—enhancing IRS signaling while reducing JAK2-mediated inflammation—suggests that GP may effectively activate the INSR–IRS2–Akt signaling axis, ultimately improving insulin sensitivity and mitigating insulin resistance." (PMID 40869401, 2025). "Both CRF and BMI-corrected HS during pregnancy were associated with lower hepatic insulin resistance (HOMA-IR), increased whole body insulin sensitivity (MATSUDA), and a lower risk of metabolic syndrome at 1-year postpartum, while HS alone was further related to lower CRP." (PMID 41276872, 2025). "Reduced HDL-c levels may diminish its protective effects on insulin signaling pathways, thereby worsening insulin resistance." (PMID 40626240, 2025). "However, the relationship between insulin resistance, defined as a defect in the insulin-mediated control of glucose metabolism, and vitiligo pathogenesis, having clinical manifestations confined to the skin, still lacks an explanation." (PMID 40277891, 2025). "Additionally, studies have shown that ACEI inhibitors can improve insulin sensitivity, increase insulin secretion, and improve insulin resistance." (PMID 40963686, 2025). "The results showed that combined magnesium-zinc-calcium-vitamin D supplementation significantly reduced fasting glucose, serum insulin, insulin resistance, and serum high-sensitivity C-reactive protein levels, and improved insulin sensitivity and total antioxidant capacity in vivo." (PMID 39963668, 2025). "Overall, our results suggest a picture of responsiveness of the intestinal epithelial monolayer to insulin in the inflammatory environment, to be investigated also in the context of conditions driven by insulin resistance and affecting functions of the enterocyte monolayer at different levels." (PMID 40940769, 2025).
Insulin resistance (continued). "Furthermore, notably, oxidative stress can exert varying degrees of damage to insulin signal transduction, disrupt insulin signaling pathways, and ultimately give rise to insulin resistance." (PMID 40842498, 2025). "Furthermore, WD/WD mice were more insulin resistant, based on the homeostatic model assessment of insulin resistance (HOMA-IR), compared to NC/WD mice, which was further aggravated by multigenerational maternal WD feeding." (PMID 40496439, 2025). "Insulin-sensitive and insulin-resistant states are mediated by tyrosine protein phosphatase nonreceptor type 6 protein (PTPN6), and reducing PTPN6 expression can modulate immune system dysfunction and insulin resistance caused by hyperinsulinemia." (PMID 41020854, 2025). "We hypothesised that higher insulin resistance is associated with CAC and conducted a systematic review of studies measuring fasting glucose and insulin to calculate HOMA-IR." (PMID 41367198, 2025). "Therefore, in a state of insulin resistance with higher circulating levels of insulin, theca cells are stimulated to produce excess androgens." (PMID 41295220, 2025). "Furthermore, more studies on other insulin in vitro insulin resistance models, including chronic high-insulin- or TNF-a-exposed cell models, are necessary to provide consolidated understanding." (PMID 41155560, 2025). "Overnutrition rapidly promotes insulin resistance in the brain, long before insulin signaling in peripheral organs is affected, suggesting that insulin resistance in the brain represents an early and important mechanism for dyslipidemia and hyperglycemia in the condition of hypernutrition." (PMID 41012462, 2025). "However, impaired insulin secretion, insulin resistance, or a combination of both is considered the core pathophysiological defect." (PMID 41011279, 2025). "Together, these findings suggest that MASLD in T1D cannot be fully explained by insulin resistance alone and is likely to result from a combination of unique factors, including insulin delivery patterns, glucagon dysregulation, autoimmune effects, and ectopic fat metabolism." (PMID 40807122, 2025). "Furthermore, a positive association was observed between insulin resistance (calculated as HOMA-IR, which incorporates both fasting insulin and glucose) and changes in fatigue (measured as FSS score)." (PMID 40218921, 2025). "Our unpublished data on insulin resistance index support that NDM rats developed T2DM, exhibiting slightly decreased insulin levels and insulin resistance in contrast to PDM, which were insulin deficient and non-resistant." (PMID 41227359, 2025). "The increased GLUT4 expression in MAT may play an important role in some of the beneficial effects of CP when associated with FRUCT, namely the reduction in plasma glucose and insulin levels, as well as the improvement in insulin resistance." (PMID 40227203, 2025). "In addition, mental disorders are associated with insulin resistance, a key pathological feature of NAFLD; long‐term psychological stress can affect insulin sensitivity, leading to abnormal blood sugar control and promoting liver fat deposition." (PMID 41031052, 2025). "Furthermore, the increased inflammatory state alters insulin sensitivity, leading to the development of insulin resistance in the endometrium of women with PCOS." (PMID 40943118, 2025). "By targeting IRS-1, IL-1β is capable of impairing insulin signaling and action and could thus participate (in combination with other cytokines) in the development of insulin resistance in adipocytes." (PMID 41012578, 2025). "Increased salt consumption induces insulin resistance, which might explain the mismatching between insulin and glucose values." (PMID 39852897, 2025). "However, it should be noted that significantly elevated serum insulin levels after food consumption not only counteract the deleterious effects of hepatic insulin resistance but also further potentiate PI3K-AKT-mTORC1 signaling pathway activation." (PMID 41407267, 2025).
Insulin resistance (continued). "The analysis revealed a significant and positive association between plasma GDF-15 levels and HbA1c (r = 0.297, p < 0.001), fasting blood glucose (FBG) (r = 0.269, p < 0.001), fasting insulin (r = 0.127, p < 0.001), and the homeostatic model of insulin resistance (HOMA-IR) (r = 0.198, p < 0.001)." (PMID 40722664, 2025). "However, in clinical practice, inadequate pancreatic β-cell function and insulin resistance also contribute to higher insulin requirements and poorer glycemic control, particularly in terms of hyperglycemic events." (PMID 40401174, 2025). "As a result, cellular sensitivity to insulin decreases, which can lead to insulin resistance." (PMID 39997933, 2025). "Insulin resistance is a condition wherein cells fail to adequately respond to insulin." (PMID 40565151, 2025). "However, by late pregnancy as insulin resistance increases due to placental hormones, the insulin response becomes inadequate." (PMID 40497429, 2025). "However, evidence of altered insulin signalling was observed in the liver, a primary tissue where insulin resistance occurs." (PMID 40617804, 2025). "Collectively, these studies suggest that combining CSII with insulin-sensitizing agents may alleviate insulin resistance and glucolipotoxicity, creating a more favorable metabolic milieu for β-cell function restoration." (PMID 41427055, 2025). "Insulin resistance is a physiological condition whereby the body’s cells become less responsive to the effects of insulin, a hormone that is essential for the regulation of blood sugar levels and facilitation of the uptake of glucose into cells, primarily muscle and fat." (PMID 39982905, 2025). "Magnesium is an important cofactor for a number of cellular functions related to insulin action and secretion, e.g., for the normal function of the insulin receptor, and it has been postulated that hypomagnesemia may contribute to insulin resistance." (PMID 39911868, 2025). "Vitamin D supplementation also significantly elevated the levels of SIRT1 and SIRT6, which play important roles in glucose homeostasis by increasing insulin secretion, inhibiting gluconeogenesis and lipogenesis and suppressing obesity-induced inflammation and insulin resistance." (PMID 39859540, 2025). "CRH oppose the insulin signal, leading to the phenotype of insulin resistance." (PMID 40421040, 2025). "In such cases, higher insulin doses are frequently required to overcome insulin resistance, which can arise during adolescence and may be further aggravated by a sedentary lifestyle." (PMID 41234236, 2025). "Furthermore, the dexamethasone insulin resistance model has been widely used to test insulin-sensitizing agents, with 5–7-day protocols reproducing impaired peripheral glucose uptake and worsening tolerance." (PMID 41155701, 2025). "Conventional therapies, including metformin, sulfonylureas, thiazolidinediones, and insulin, have proven effective in many instances, offering various mechanisms of action to address the underlying causes of T2DM, such as insulin resistance and beta-cell dysfunction." (PMID 40395625, 2025). "However, insulin resistance reduces cellular responsiveness to insulin, necessitating increased insulin levels to maintain normal blood glucose levels." (PMID 40260393, 2025). "Furthermore, patients with cirrhosis exhibit reduced hepatic insulin clearance and increased diversion of insulin from the portal to the systemic circulation, thus contributing to insulin resistance and the progression of MASLD." (PMID 40444235, 2025). "Olanzapine induces insulin resistance (IR) by suppressing brown adipose tissue thermogenesis, damping expression of mitochondria uncoupling protein-1 and inhibiting glucose transporters, leading to impaired glucose uptake and decreased response to insulin." (PMID 40229885, 2025).
Insulin resistance (continued). "Data from clinical investigations of FMT have shown that after 6 weeks of FMT intervention, lean-donor FMT can help MetS participants lose weight (including visceral fat), improve insulin resistance and peripheral insulin sensitivity, and lower subjects' blood pressure." (PMID 40583967, 2025). "For example, an in vivo study found that administration of okra fruit extract (200 mg/kg) significantly suppressed insulin levels, the homeostasis model assessment of basal insulin resistance (HOMA-IR), as well as blood glucose levels in streptozotocin-induced diabetic rats." (PMID 39856844, 2025). "Compared to hs-CRP and TNF-α, which are elevated in PCOS and indicate a pro-inflammatory state, adiponectin functions as an anti-inflammatory regulator, where it counteracts insulin resistance and systemic inflammation effects by enhancing insulin sensitivity and reducing inflammation." (PMID 40385768, 2025). "The main features are a systemic inflammatory condition accompanied by hyperglycemia and insulin resistance (IR) or a decreased metabolic response to insulin in tissues such as skeletal muscle, adipose tissue, and the liver, with reduced insulin synthesis by pancreatic beta cells." (PMID 41154476, 2025). "Beyond systemic plasmatic insulin resistance measurement, evaluating insulin sensitivity post-exercise in peripheral organs where insulin resistance may occur should also be interesting." (PMID 40943107, 2025). "Insulin resistance is characterized by a diminished cellular response to insulin." (PMID 39940428, 2025). "In particular, hypertrophied adipose tissue resulting from obesity, along with adipose tissue-resident immune cells, increases circulating pro-inflammatory cytokines, inducing chronic inflammation that impairs insulin signaling pathways and exacerbates insulin resistance." (PMID 39851765, 2025). "Within healthy volunteers, IHL correlated positively with VLDL-TG secretion rate (rho = 0.66, P < .001) as with other metabolic biomarkers, including BMI, relative fat mass, serum triglycerides, insulin, and homeostatic model assessment for insulin resistance (HOMA-IR)." (PMID 40215215, 2025). "As the primary mediators, the inflammatory factors TNF-α and IL-6 cooperated with other factors to inhibit or damage insulin secretion by pancreatic islet beta cells and simultaneously reduce the activity of insulin receptors, thus leading to insulin resistance." (PMID 40842498, 2025). "The ST3GAL2 deficiency disrupted insulin signaling by impairing insulin receptor-mediated phosphorylation in adipose tissue but not liver or skeletal muscle, leading to hyperglycemia and insulin resistance." (PMID 41301440, 2025). "The mechanistic link explaining how the over‐accumulation of larger LDs in the SS region of the myocyte induces insulin resistance is still unclear, but the proximity of these large LDs to the muscle membrane may disrupt key insulin signalling processes." (PMID 39487600, 2025). "Abdominal obesity is related to insulin resistance, and previous work from our laboratory showed that MetS rats developed hyperinsulinemia and impaired insulin-induced glucose uptake by isolated cardiomyocytes, a finding corroborated in cardiomyocytes from MetS patients." (PMID 40869310, 2025). "This discovery suggests that in environments with HUA, insulin resistance may intensify, leading to increased insulin secretion to maintain blood sugar stability, but the effect is limited, which in turn promotes sustained increases in blood sugar." (PMID 40092731, 2025). "Notably, the frequency of insulin-specific CD8 T cells positively correlated with HOMA-IR (r = 0.54, p = 0.01) and Matsuda index (r = -0.56, p = 0.009), suggesting a link between insulin resistance and insulin-specific CD8 T cells." (PMID 39656436, 2025). "Therefore, brain insulin resistance comes from the downregulation of IR or an incorrect activation of the insulin signaling cascade, mainly driven by IRS-1 inhibition." (PMID 40362446, 2025).